PMS2 (PMS1 homolog 2, mismatch repair system component)
Diseases named in the same sentence as PMS2 in open-access papers (continued):
Sharing a sentence is not in itself a finding about the gene and the disease.
Lynch syndrome (continued). "According to the study, MSI presence in the young patients was not strongly associated to MLH1/PMS2 loss and did not co-exist with BRAFV600E mutations (p < 0.01), which suggests more frequent occurrence of the Lynch syndrome in the subgroup of patients with the early onset of the disease." (PMID 28067827, 2017). "This redundancy also may help to explain the low prevalence and penetrance of PMS2 mutations in MMR-deficient colon cancers and the reported lack of biochemical data to support MLH3 in Lynch syndrome." (PMID 23450065, 2013). "Among all patients with CRC who had a loss of MLH1/PMS2 with BRAF V600E or MLH1 promoter hypermethylation, 2 of 16 were ultimately found to have a pathogenic germline mutation, but neither of these patients had Lynch syndrome, with one having an increased risk allele for prostate cancer." (PMID 37509234, 2023). "However, SH could not be termed as an extracolonic manifestation of Lynch syndrome since it obviously showed a benign behavior and did not exhibit MSI or loss of MMR-expression based upon heterozygosity of PMS2." (PMID 21645337, 2011). "For the seven non-Lynch syndrome cases where only blood-based testing was completed, no constitutional MLH1 epimutation was identified, suggesting that a somatic aetiology likely explains the MLH1/PMS2-deficiency in these cases but could not be confirmed due to insufficient tissue DNA." (PMID 40208414, 2025).
colorectal cancer (142 papers, 2005 to 2026). A primary or metastatic malignant neoplasm that affects the colon or rectum. "While heterozygous GVs in POLE and PMS2 cause polymerase proofreading-associated polyposis or hereditary non-polyposis colorectal cancer, respectively, predisposing to colorectal cancer, they have also been linked to glioma risk, in line with our data." (PMID 41546701, 2026). "Conversely, isolated loss of PMS2 expression is considered a rare phenotype in colorectal cancers, accounting for approximately 4% of MSI-positive tumors in Western populations and 7.9% in southern China." (PMID 41041321, 2025). "In two recently published siblings with polyposis and a first colorectal cancer diagnosis as teenagers, a heterozygous PMS2 PV and a heterozygous POLD1 exonuclease domain variant were found." (PMID 39031223, 2024). "Included in these was the PMS2 c.924G>C missense variant, which we discovered herein to comprise 20% of our PMS2 VUSs for individuals with early-onset colorectal cancer who identified as Black." (PMID 39656055, 2024). "For example, those with a PV in MLH1 have a 71-90% lifetime risk of any Lynch cancer and a 35-90% lifetime risk of colorectal cancer whereas those with a PV in PMS2 have a 34-52% lifetime risk of any Lynch cancer and a 12-52% risk of colorectal cancer." (PMID 36937421, 2023). "Colonic polyposis commonly accompanies biallelic PMS2 variants, whereas monoallelic PMS2 variants typically manifest themselves as (late-onset) colorectal carcinoma." (PMID 36387175, 2022). "The simultaneous occurrence of the G/A genotype of the MSH6 gene and the C/C genotype of the PMS2 gene was found to increase the risk of colorectal cancer (OR = 1.78 95% Cl: 1.07–2,98 p = 0.029)." (PMID 28451866, 2018). "Adding location of colorectal cancer to PREMM5 considerably improved the models performance for PMS2 mutation carriers (AUC 0.77) and overall (AUC 0.81 vs. 0.72)." (PMID 28933000, 2018). "Because the maternal lineage includes two colorectal carcinomas in two of the index person’s second-degree relatives, diagnosed at 37 and 70 years of age, the PMS2 variant is primarily suggestive of being responsible for the familial cancer phenotypes." (PMID 30086788, 2018). "The PMS2 gene encodes a DNA mismatch repair endonuclease and mutations have been associated with malignancies, in particular colorectal cancer." (PMID 24386384, 2013).
colorectal cancer (continued). "In conclusion, using the P008-B1 PMS2 MLPA kit and a set of selected reference DNAs that are universally available, we identified deleterious PMS2 alterations in 23% of our PMS2-deficient colorectal cancer patients (27% of those undergoing first-line testing)." (PMID 22585707, 2012). "Another essential MMR gene, PMS2, was previously thought to play only a minor role in colorectal cancer predisposition." (PMID 22585707, 2012). "Interestingly, PMS2 mutations were previously associated with the occurrence of secondary malignancies such as colorectal carcinoma in cHL survivors after systemic polychemotherapy." (PMID 39992429, 2025). "Similarly, some institutions routinely test for BRAF variants, instead of or in addition to MLH1 promoter methylation, in colorectal cancer with MLH1/PMS2 loss by IHC." (PMID 38344144, 2023). "Similarly, the co-existence of the BRCA2 and PMS2 mutations prompted the development of breast and colorectal cancer in the same patient." (PMID 36232793, 2022). "We found classical NTRK fusions were highly enriched in MLH1/PMS2 deficient colorectal carcinomas." (PMID 33996597, 2021). "Furthermore, studies in unselected cohorts of colorectal cancer patients have demonstrated a higher prevalence of PMS2-associated LS than previously thought." (PMID 29308099, 2018). "The purpose of the study was to evaluate the association between gene polymorphisms Glu39Gly (c.116G > A) of MSH6 gene and IVS1-1121C > T of PMS2 gene and sporadic colorectal cancer risk, in a case-control study comprising 200 patients and 200 controls origination from polish population." (PMID 28451866, 2018). "For example, one participant was at increased risk of colorectal cancer due to an affected maternal grandmother and aunt and carried a PMS2 p.R813W variant of unknown significance which is rare in the population and predicted to be deleterious by in silico models." (PMID 33413596, 2021). "For example, MSI testing may both be less specific in older patients (where somatic MLH1 hypermethylation is known to be more common in colorectal cancer) and may be less sensitive to identify path_MSH6 and path_PMS2 cases (i.e., pathogenic variants in MSH6 and PMS2)." (PMID 32492863, 2020). "Among individuals with mutations in CHEK2, BRCA2, PMS2, and APC, a high proportion reported a family history of breast, ovarian, prostate, pancreatic, or colorectal cancer (8 out of 11 considered patients)." (PMID 41294693, 2025). "Colorectal medullary carcinoma (MC) is a rare and distinct subtype of colorectal cancer associated with mismatch repair (MMR) deficiency with the loss of MLH1 and PMS2 genes." (PMID 40151739, 2025). "Thus, understanding of microsatellite instability (MSI) detection in colorectal carcinomas (CRCs) using immune histochemical markers MSH6 and PMS2, improving diagnostic and prognostic approaches for CRC." (PMID 41907888, 2025). "This test uses antibodies against four MMR proteins (MLH1, MS2, MSH6, and PMS2) to assess their expression in colorectal cancer tissue." (PMID 39741510, 2024). "The two protein losses have been far the most frequent in the dMMR cohort (70%) and the PCR discrepancy was the lowest in case of the MLH1/PMS2 phenotype in case of the colorectal cancers exclusively." (PMID 38350968, 2024). "The risks of all cancers for PMS2 PV carriers are especially modest, in particular for colorectal cancer." (PMID 38356732, 2024).
colorectal cancer (continued). "The index case was a French 73‐year‐old man diagnosed with colorectal cancer displaying microsatellite instability and the loss of MLH1 and PMS2 expression." (PMID 37350751, 2023). "Methylation of the MLH1 promoter is the most common cause of MMRd and microsatellite instability (MSI) in both colorectal cancer and endometrial cancer and is routinely evaluated in tumors that show loss of MLH1 and PMS2 by IHC." (PMID 38344144, 2023). "Two breast cancer women that are double heterozygotes (DH) for both BRCA1/BRCA2, one ovarian cancer case DH for BRCA1/RAD51C, and another breast and colorectal cancer who is DH for BRCA2/PMS2 were identified in our cohort." (PMID 36232793, 2022). "Low-expressed PMS2 protein was also observed in one out of 10 cases of colorectal cancer in our previous study cohort, and other MMR proteins were all highly expressed in all samples (data not shown)." (PMID 33717059, 2021). "Our previous study regarding mutations in DNA-repair-associated genes in colorectal cancer demonstrated that EMAST+/MSI-H tumors had a higher frequency of MLH1, MSH3, MSH6, PMS2, and EXO1 genetic mutations than the other three colorectal cancer subtypes." (PMID 32120855, 2020). "In colorectal carcinoma, MMR-proficiency tumors were predictors of longer disease-free survival compared to any loss of MMR protein expression (p < 0.05), especially MLH1/PMS2 loss (p < 0.01)." (PMID 33302424, 2020). "Among the MMR-proficient tumors, at least 8% had a germline in at least one gene (in some cases, mutations in high-penetrance colorectal cancer genes, such as APC, PMS2, MUTYH, SMAD4)." (PMID 29652830, 2018).
colorectal cancer (continued). "Among the patients with PMS2 mutations, two (P1 and P6) had been diagnosed with colorectal cancer as first malignancy only in their early twenties, supporting the notion of less penetrant forms of CMMRD especially in PMS2-deficient individuals." (PMID 30013564, 2018). "In recent years, a two-antibody panel approach using PMS2 and MSH6 was proposed as an effective screening protocol for colorectal carcinoma with mismatch repair protein deficiency." (PMID 28451866, 2018). "The inversion region encompasses more than 15 RefSeq genes, including the PMS2 gene, known to be involved in colorectal cancer." (PMID 16254605, 2005). "Similarly, loss of MMR genes such as MLH-1, PMS-2, MSH-2 and MSH-6 leads to MSI and increases the risk of colorectal cancers (CRC)." (PMID 38134458, 2023). "Diseases associated with PMS2 mutation include colorectal cancer, hereditary nonpolyposis, type 4 and Mismatch Repair Cancer Syndrome." (PMID 35202347, 2022). "Therefore, in the medical care for colorectal cancer, if the dMMR-testing result shows MSI-H or the loss of MLH1/PMS2 expression, checking for the BRAF V600E mutation helps distinguish Lynch-associated colorectal cancers from sporadic ones." (PMID 31286289, 2020). "Deletion was believed to be the most frequent mutation of PMS2, which was previously referred to as hereditary nonpolyposis colorectal cancer and other types of malignancy." (PMID 31391089, 2019). "For example, 50% of the ‘Gene: MLH1’ subpopulation had colorectal cancer before age 50 years, with a mean onset age at 44 ± 14.25 years, compared to 0% of the ‘Gene: PMS2’ subpopulation that had colorectal cancer before age 50 years, with a mean onset age at 57 ± 4.36 years." (PMID 30759220, 2019). "Additionally, when DSBs are induced by gamma-radiation, Mlh1, Pms2 and Mlh3 mutant MEFs have higher DR copy number alterations (CNAs), including DR CNA hotspots previously identified in mouse MMR-deficient colorectal cancer (dMMR CRC)." (PMID 29069730, 2017). "The constellation of colorectal cancer and brain tumours, in particular glioblastomas, are associated with Turcot syndrome, a rare molecularly heterogeneous syndrome caused by mutations in the MLH1 and PMS2 genes." (PMID 25133505, 2014).